ELN (elastin)
Diseases named in the same sentence as ELN in open-access papers (continued):
Sharing a sentence is not in itself a finding about the gene and the disease.
acne (4 papers, 2024 to 2025). An inflammatory process of the sebaceous glands which is characterized by comedones, nodules, papules and/or pustules on the skin. "Often combined with microneedling, creating tiny punctures in the skin to stimulate the body's natural healing process and enhance collagen and elastin production, mesotherapy further aids in reducing the appearance of acne scars." (PMID 40314127, 2025). "With acne scars, dermal collagen and elastin disruption and disorganized dermal architecture contribute to its clinical appearance." (PMID 41428599, 2025). "In a recent study, the use of topical epidermal growth factor ointment was found to stimulate elastin, collagen 1, and collagen 3 production within acne scars, leading to clinical improvements." (PMID 38904694, 2024). "Additionally, it suggests the potential for CBD to contribute to the improvement of acne scarring through the synthesis of collagen and elastin." (PMID 38904694, 2024). "By modulating key structural genes like ELN, FN1, EGFR, and TIMP3, F3TAC supports ECM remodeling and wound healing, essential for addressing inflammation and tissue repair in acne-prone skin." (PMID 39684852, 2024).
amyloidosis (4 papers, 2013 to 2023). A disorder characterized by the localized or diffuse accumulation of amyloid protein in various anatomic sites. "Medin-associated vascular cell apoptosis and necrosis; medin-associated elastin degeneration, calcification, and amyloidosis result in a weakness of the vascular wall." (PMID 36672188, 2023). "In addition, both MFG-E8 and medin interacts with degenerated elastic fibers, suggesting that elastin-derived fragments are probably important elements in the formation of MFG-E8/medin-associated amyloidosis, and significantly affect the elasticity of elastic fibers." (PMID 36672188, 2023). "Therefore, increased elastin fiber in the blood vessel wall and amyloidosis were observed in the tongues of klotho−/− mice compared to klotho+/+ mice." (PMID 28885690, 2018).
Arthritis (4 papers, 2018 to 2023). Inflammation of a joint. "FMRP is known to regulate multiple connective tissue pathways including elastin, actin, and matrix metalloproteinase (MMP9), a class of enzymes involved in bone development, wound healing, and pathology such as arthritis and intracerebral hemorrhage." (PMID 35126193, 2021).
autoimmune disease (4 papers, 2011 to 2025). A disorder resulting from loss of function or tissue destruction of an organ or multiple organs, arising from humoral or cellular immune responses of the individual to their own tissue constituents. "In this respect, it is noteworthy that a recent hypothesis has suggested that COPD is an autoimmune disease in which anti-elastin, epithelial, and endothelial cell antibodies promote disease progression especially in patients with severe disease." (PMID 27994288, 2016).
coronary artery disease (4 papers, 2019 to 2025). "ECM remodeling is essential for the progression of proliferative diabetic retinopathy (PDR) and is also a key factor in coronary artery disease, where the degradation of ECM components such as collagen, elastin, and proteoglycans is associated with inflammatory responses." (PMID 40176795, 2025).
keratoconus (4 papers, 2016 to 2025). A degenerative, structural disorder of the eye, characterized by a cone-shaped protrusion of the cornea. "Furthermore, elastin is considered to be pivotal in the disease progression, as keratoconus typically starts with a posterior elevation affecting these two layers." (PMID 40837574, 2025). "Reduced expression of elastin occurs in the corneal stroma of patients with keratoconus (KC)." (PMID 40837574, 2025). "Interestingly, we also find decreased elastin fibers in upper and mid dermis of three patients with keratoconus in histopathology evaluation of skin samples." (PMID 27403376, 2016). "Although differences in the distribution of microfibrils have been identified in eye diseases, such as keratoconus, limited ophthalmological research has focused on the mechanisms involved in the assembly of elastin, and no studies have directly focused on pterygium." (PMID 34945227, 2021). "The significant reduction of elastin in the PDL/DL and DM in cases of advanced keratoconus with acute corneal hydrops (ACH) may play a crucial role in the pathology of KC and the subsequent onset of ACH." (PMID 40837574, 2025).
liver cirrhosis (4 papers, 2016 to 2024). "LOXL1, a member of the lysyl oxidase (LOX) family of enzymes involved in collagen and elastin crosslinking, has also been linked to liver cirrhosis." (PMID 38565287, 2024). "We applied the statistical detection method to the detection of brown colour in liver cirrhosis biopsies stained for elastin fibres." (PMID 27121383, 2016).
Myocardial fibrosis (4 papers, 2010 to 2020). "Morphological examination demonstrated excessive myocardial fibrosis and disruption of the elastin components of the matrix architecture." (PMID 22435995, 2012). "The extracellular matrix (ECM) comprises collagen, laminin, elastin and fibronectin abnormally elevated ECM deposition, especially collagen deposition, results in myocardial fibrosis." (PMID 32611270, 2020).
prostate carcinoma (4 papers, 2014 to 2024). A carcinoma that arises from epithelial cells of the prostate gland. "In this study, size, shape, surface charge, chemical composition, thermal stability, and other properties of ENG were used to confirm the successful synthesis and incorporation of Decursin (DEC) into elastin nanogels (ENG) for prostate cancer therapy." (PMID 38956125, 2024). "The present study examined prostate cancer in a xenograft mouse model using an elastin-specific molecular probe for magnetic resonance molecular imaging." (PMID 34827210, 2021). "Our study demonstrates that molecular imaging using an elastin-specific gadolinium-containing contrast agent is feasible in prostate cancer." (PMID 34827210, 2021). "This study aimed to investigate collagen (Coll-I, III, IV) and elastin in canine normal prostate and prostate cancer (PC) using Picrosirius red (PSR) and Immunohistochemical (IHC) analysis." (PMID 30832371, 2019). "However, the novelty of this study lies in the fact that DEC has been first time explored in an elastin -based nanocarrier for prostate cancer therapy, marking a significant advancement in the field." (PMID 38956125, 2024). "This study aimed to use a low-molecular elastin-specific probe in MRI examinations and, thus, to obtain information on changes in the ECM during prostate cancer development for a better differentiation between tumor tissue and healthy tissue." (PMID 34827210, 2021). "There are no reports of elastin fibers and prostatic cancer in different species, so the biological role of the increase of elastic fibers should be further investigated." (PMID 30832371, 2019).
Stress urinary incontinence (4 papers, 2021 to 2024). Involuntary urine leakage synchronous with exertion, or actions such as sneezing, or coughing. "Increasing attention in research has been directed towards understanding the role of elastin in the pathophysiological development of PFD, particularly in stress urinary incontinence and POP, both of which are linked to injuries sustained during childbirth." (PMID 38898783, 2024). "Stress urinary incontinence primary fibroblasts or satellite cells were treated with ADSCs-extracellular vesicles to detect the expression of Elastin, Collagen I, and Collagen III in fibroblasts and Pax7 and MyoD in satellite cells." (PMID 34484115, 2021). "ADSCs-extracellular vesicles treatment upregulated expression of Elastin, Collagen I, and Collagen III in stress urinary incontinence primary fibroblasts and expression of Pax7 and MyoD in stress urinary incontinence primary satellite cells." (PMID 34484115, 2021). "Crosslinked and non-crosslinked hyaluronic acids have also been studied in stress urinary incontinence, both as regenerative factors—increasing collagen and elastin levels in the urethral region—and as volumetric factors—narrowing the urethral lumen after transurethral injection." (PMID 38794192, 2024).
tendinopathy (4 papers, 2013 to 2023). "In conclusion, four strong candidate genes (COL11A2; ELN; ITGB3; LOX) were identified as differentially expressed in tendinopathy, functionally linked to features of tendinopathy and implicated in the aetiology of other connective tissue diseases." (PMID 26804977, 2016). "The current study identified four strong candidate genes (COL11A2; ELN; ITGB3; LOX) that are differentially expressed in tendinopathy, functionally linked to features of tendinopathy and previously implicated in the aetiology of other connective tissue diseases." (PMID 26804977, 2016).
ulcer (4 papers, 2011 to 2023). "In an advanced stage, the reduction of acidity and gastric juice secretion under the effect of OFI oil would promote ulcer healing by filling then remodelling the extracellular matrix with structural proteins such as collagen types I, II, and III and elastin, proteoglycans, and hyaluronans." (PMID 31827668, 2019). "Relative ulcer volume (RUV) was measured every month; biopsies were taken at baseline and months 1 and 2 for histopathology and gene expression analysis for COL-1α, COL-4, KGF, VEGF, ACTA2 (α-SMA), elastin, fibronectin, TGF-β1, TGF-β3, HIF-1α, and HIF-1β." (PMID 29675430, 2017).
Airway obstruction (3 papers, 2021 to 2025). Obstruction of conducting airways of the lung. "Conversely, increased levels of C4M and ELP‐3 in patients with airway obstruction highlight the role of type IV collagen and elastin degradation, primarily driven by PR3 activity rather than NE." (PMID 40760731, 2025).
Alzheimer disease (3 papers, 2019 to 2022). A progressive, neurodegenerative disease characterized by loss of function and death of nerve cells in several areas of the brain leading to loss of cognitive function such as memory and language. "The immune cells recognize EDPs as a foreign antigen and produce anti-elastin antibodies that result in an autoimmune reaction as seen during psychiatric diseases and other neurodegenerative disorders such as Alzheimer’s disease." (PMID 36140268, 2022). "Treatment with elastin polypeptides, a component of the brain extracellular matrix (ECM), increases levels of β‐amyloid, associated with Alzheimer's disease, both in vitro and in vivo." (PMID 31609093, 2019). "A recent study showed that elastin in the brain might induce pathological changes in Alzheimer’s disease, and elastin is known to be fragmented and released with aging." (PMID 34502277, 2021).
Atrophy (3 papers, 2018 to 2024). Any weakening or degeneration, especially through lack of use. "The decrease in estrogen levels results in a decrease in vaginal epithelial permeability, perfusion, and elastin levels, resulting in vaginal dryness and atrophy." (PMID 34066357, 2021). "Notably, collagen and elastin are the main constituents of Bruch’s membrane between the RPE and choroid, where atrophy occurs in myopic maculopathy." (PMID 29725004, 2018).
breast tumors (3 papers, 2018 to 2024). "As a consequence, this work suggests that an environmental factor derived from an aged stroma or elastosis (elastin fragments) could possibly influence breast tumor progression by mobilizing greater amounts of active MMPs thereby modifying tumor cell invasive capacity." (PMID 30186741, 2018).
calcification (3 papers, 2020 to 2023). Process by which organic tissue becomes hardened by the physiologic deposit of calcium salts. "Aortic calcification in the tunica media is correlated with aortic stiffness, elastin degradation, and wall shear stress." (PMID 35148346, 2022). "The chelating ability of the DTPA-(HSA-NP)-IgG was less effective than the chelating ability of the DTPA-(HSA-NP)-AntiElastinPig, as the NPs with the specific antibody directed against elastin could connect to the valve’s elastic fibers, the location where calcifications were present." (PMID 38003660, 2023).
Cognitive impairment (3 papers, 2016 to 2025). Abnormal cognition is characterized by deficits in thinking, reasoning, or remembering. "Vibroacoustic disease is associated with abnormal growth of extracellular matrices (collagen and elastin) in the absence of an inflammatory process, as well as depression, irritability and cognitive impairment." (PMID 39957718, 2025).
colitis (3 papers, 2015 to 2023). Inflammation of the colon. "This derangement of collagen/elastin network might well contribute to bowel motor dysfunctions, contributing to weight loss, which is a hallmark of animals with colitis 2,15." (PMID 25521239, 2015). "While MMP12 was previously shown to be critical for Mφ transmigration across intestinal epithelial cell layers in severe colitis, we found that MMP12 attenuates Mφ mobility on Matrigel/elastin-coated surfaces resembling structural features of the ECM." (PMID 38069304, 2023).
cystic fibrosis (3 papers, 2022 to 2024). Autosomal recessive disorder caused by pathogenic variants in the CFTR gene (cystic fibrosis transmembrane conductance regulator), which encodes a chloride and bicarbonate channel expressed in epithelial cells, and follow the diagnosis criteria. "Interestingly, similar to collagen, the concentrations and synthesis of elastin were also found to be higher in patients with cystic fibrosis and COPD, conditions that are often associated with biofilms of P. aeruginosa and S. aureus." (PMID 38337187, 2024).
disc degeneration (3 papers, 2019 to 2022). "Disc degeneration was associated with a significant increase in elastin abundance, while scoliosis resulted in a significant decrease in collagen." (PMID 31332239, 2019). "While unknown disc origin may have influenced several studies, in 2007 Cloyd and Elliott reported that elastin content actually increased with disc degeneration, which would apparently contradict data from studies involving other joints." (PMID 31220091, 2019).
diverticulitis (3 papers, 2022 to 2023). An infection that develops in the diverticula of the intestinal tract. "WS is caused by the loss of elastin on chromosome 7, one of the main roles of which is to maintain the strength and elasticity of the intestinal wall, and the loss of this protein gene may be the main cause of diverticulitis." (PMID 37337730, 2023). "One of the main roles of this gene is to maintain the strength and elasticity of the intestinal wall, and the absence of the elastin gene may predispose these patients to gastrointestinal pathology such as diverticulitis." (PMID 35936144, 2022).
hepatic cancer (3 papers, 2020 to 2021). "In conclusion, our data confirm the diagnostic potential of the elastin-specific targeted MRI for imaging and quantitative assessment of the intra- and peritumoral matrix in a hepatic cancer animal model." (PMID 33247185, 2020). "Non-invasive MR imaging using the elastin-specific molecular probe produced image data with a high spatial resolution and clear contrast enhancement in the viable tumor regions, thus underlining the priority of targeted MRI in hepatic cancer research." (PMID 33247185, 2020). "We report for the first time that LOC644135, ELN, GULP1, ENSG00000248635, GPM6A, and PI15 are associated with the risk of liver cancer recurrence." (PMID 34956309, 2021). "An elastin-specific contrast agent has not only shown good results in cardiovascular diseases but could also be used for the detection of malignant liver tumors." (PMID 34827210, 2021). "Additionally, hepatic cancer could be evaluated using an elastin-specific MRI molecular probe." (PMID 34827210, 2021). "The aim of this study was to test the potential of an elastin-specific molecular MR probe to assess and quantify the peritumoral matrix in a rabbit VX2 hepatic cancer model." (PMID 33247185, 2020).
Hyperkeratosis (3 papers, 2021 to 2024). Hyperkeratosis is a histopathological term defining a thickened stratum corneum and may be present in many different skin conditions, with many possible overlaps. "Similarly, many older adult individuals experience hyperkeratosis and region-specific foot pain due to the loss of elastin and collagen fibers in the plantar surface." (PMID 38962776, 2024). "Continuous UV irradiation can induce epidermal and dermal changes in hairless mouse skin, including hyperkeratosis, acanthosis, dermal perivascular inflammatory cell infiltration, the excessive deposition of the abnormal elastin complex, and (most importantly) the impairment of collagen fibers." (PMID 34677449, 2021).
hyperlipidemia (3 papers, 2022 to 2024). "The metabolic processes, synthesis, secretion, crosslinking, degradation, and regeneration of elastin are likely altered by the pathological environment of hyperlipidemia, which may be a potential cause of the observed elastin damage." (PMID 38992615, 2024).
hyperphosphatemia (3 papers, 2019 to 2023). Abnormally high level of phosphate in the blood. "As CKD progresses to late stages, hyperphosphataemia causes further weakening of the vessel wall and arterial calcification by inducing an osteogenic phenotype shift of SMC and elastin degradation in the medial layer." (PMID 36564356, 2023). "Along those lines, excessive levels of the cysteine protease cathepsin S leads to cleavage of elastin and generation bioactive elastin peptides, which may act directly on VSMCs to further accelerate vascular calcification during hyperphosphatemia." (PMID 30887097, 2019).